SNORD72 (small nucleolar RNA, C/D box 72)
Synonyms: HBII-240
Gene: Small nucleolar RNA gene on chromosome 5 (40,832,656 to 40,832,735, reverse strand). Ensembl gene ENSG00000212296.
Gene Ontology:
Biological process: RNA processing
Cellular component: nucleolus
Homologues: Orthologues: macaque SNORD72 (99% identical), pig SNORD72 (94% identical), dog SNORD72 (91% identical), mouse Snord72 (90% identical), rat Snord72 (89% identical), guinea pig SNORD72 (86% identical), tropical clawed frog SNORD72 (76% identical), rabbit SNORD72 (74% identical).
Diseases named in the same sentence as SNORD72 in open-access papers:
SNORD72 is named in the same sentence as 2 diseases in open-access papers, as found by Europe PMC text mining. Sharing a sentence is not in itself a finding about the gene and the disease. The quoted sentences say what the papers report.
liver cancer (1 paper, 2022). An epithelial or non-epithelial malignant neoplasm that arises from the liver. "Previously the upregulation of SNORD72 has been reported to distinguish cancer from normal counterparts and to promote liver cancer cell invasiveness via stabilizing ID2 mRNA, whereas SNORD92 has been linked to BC patient outcome." (PMID 36585466, 2022).
SNORD72 also shares sentences with these, for which no sentence is quoted: cancer (3 papers).